PCBP1 (poly(rC) binding protein 1)
Diseases named in the same sentence as PCBP1 in open-access papers (continued):
Sharing a sentence is not in itself a finding about the gene and the disease.
hepatocellular carcinoma (7 papers, 2007 to 2024). A malignant tumor that arises from hepatocytes. "To determine whether PCBP1 is directly involved in transcription, we utilized PCBP1 ChIP-sequencing datasets from the ENCODE database for both HepG2 (human hepatocellular carcinoma) and K562 (human myelogenous leukemia) cells." (PMID 39342995, 2024). "In the present study, we provide convincing evidence that human PCBP1 regulates CD44 alternative splicing in human hepatoma cell line HepG2 cells, and loss of PCBP1 in human hepatic tumor may contribute to the formation of a metastatic phenotype." (PMID 20361869, 2010). "To confirm the inhibition of CD44 v6 expression by PCBP1, we performed the assays in another hepatocellular carcinoma cell line SMMC-7721 cells and the similar results were obtained." (PMID 20361869, 2010). "PCBP1 (alpha CP1 or hnRNPE1) has been characterized as a negative regulator of CD44 variants splicing in the human hepatoma cell line HepG2." (PMID 38106992, 2023). "Current evidence is limited to the regulation of (i) Snail by hnRNP-A2/B1 and hnRNP-F, respectively, in lung and bladder cancer cells, (ii) disabled-2 (Dab2) and interleukin-like EMT inducer (ILEI) by hnRNP-E1 in mammary gland cells, and, finally, (iii) invasion by PCBP-1 in hepatoma cells." (PMID 35055098, 2022). "PCBP1 inhibits the invasion of hepatocellular carcinoma (HCC) cells, but there are few studies on the specific regulatory target and mechanism of RBPs in HCC, and it is unclear whether PCBP1 plays a role in tumour metastasis as a splicing factor." (PMID 34857818, 2021).
prostate carcinoma (6 papers, 2014 to 2026). A carcinoma that arises from epithelial cells of the prostate gland. "In prostate cancer, a novel risk model comprising five genes, namely poly(rC) binding protein 1 (PCBP1), PABPN1, protein tyrosine phosphatase receptor type F (PTPRF), differentiation antagonizing non-protein-coding RNA (DANCR), and MYC, was established for predicting progression-free survival (PFS)." (PMID 40607380, 2025). "As PCBP1 has been previously found to regulate the androgen receptor in androgen-responsive cells, like the prostate cancer LNCaP cells, this connection might be underlying the function of PCBP1 in ovarian tumor biology as well." (PMID 25265318, 2014). "In prostate cancer, BCAT2 physically interacted with PCBP1 at position leucine 239 through hydrogen‐bond networking, and their complex cooperatively activated the PI3K/AKT signaling pathway." (PMID 41457818, 2026). "In prostate cancer, TGF-β1 enhances tumour stemness by downregulating expression of PCBP1." (PMID 35907982, 2022).
cervical carcinoma (5 papers, 2018 to 2024). A carcinoma arising from either the exocervical squamous epithelium or the endocervical glandular epithelium. "Studies have shown that the overexpressed tumor suppressor PCBP1 favored the production of long isoforms of p73 in human cervical carcinoma cells, thereby inducing upregulated ratio of Bax/Bcl-2, the release of cytochrome c and the expression of caspase-3." (PMID 38933923, 2024). "However, there are also reports that PCBP1 overexpression elicits cycle arrest, apoptosis induction, and p73 splicing in human cervical carcinoma cells." (PMID 38218813, 2024).
viral infection (5 papers, 2014 to 2024). "TAX1BP1 regulates MAVS degradation under physiological conditions and during viral infection in a similar manner to PCBP1/2." (PMID 32536927, 2020). "In most cases, viral infection induces apoptosis, but although the mechanism is unclear, PCBP1 may be a potential target for initial investigation.PCBP1 overexpression had little effect on cell cycle in PK-15 cells." (PMID 38218813, 2024). "Therefore, we intend to conduct in-depth research on porcine PCBP1, hoping to find new directions for the prevention and control of porcine viral diseases." (PMID 38218813, 2024). "In addition, PCBP1 plays a physiological role by mediating housekeeping degradation of mitochondrial antiviral signaling (MAVS) as a feedback inhibitor of antiviral immunity after viral infection." (PMID 24489926, 2014). "Studies have shown that poly(rC)-binding protein 1 (PCBP1) is recruited to the cGAS protein to increase its activity and enhance the affinity of cGAS for its ligand during viral infection." (PMID 38782895, 2024). "The difference is that PCBP1 is stably expressed both in viral and resting states, while the basic expression of PCBP2 overlaps, but it is rapidly induced after the virus infection." (PMID 34566944, 2021). "To increase our understanding for the role of PCBP1 during EV71 replication, we investigated the sub-cellular distributions of PCBP1 protein, and EV71 RNA during viral infection." (PMID 24489926, 2014). "Recent work has established a similar role for the highly homologous PCBP1; however, PCBP1 expression level does not appear to be altered during viral infection." (PMID 32536927, 2020).
head and neck cancer (4 papers, 2023 to 2024). A primary or metastatic malignant neoplasm affecting the head and neck. "PCBP1 knockdown was found to promote polyunsaturated fatty acid peroxidation and ferroptosis-induced cell death in head and neck cancer and bladder cancer." (PMID 39170746, 2024). "A recent study showed that poly(rC)-binding protein 1 repressed ferritinophagy-mediated ferroptosis through binding to CU-rich elements in 3′-UTRs of BECN1 mRNA in head and neck cancer." (PMID 37522124, 2023). "In head and neck cancer cells, knockdown of the cytosolic iron chaperone poly (rC)-binding protein 1 (PCBP1) increased BECN1 mRNA stability and inhibited xCT expression and viability, thereby promoting ferroptosis." (PMID 37745084, 2023).
liver cancer (4 papers, 2010 to 2023). An epithelial or non-epithelial malignant neoplasm that arises from the liver. "The varied expression levels of DEFRGs between the tumor and control groups in the TCGA-LIHC liver cancer dataset were compared, where ZFP36, NCOA4, FTH1, FTL, TNF, and PCBP1 were matched with the TCGA transcriptome data." (PMID 37555866, 2023). "Furthermore, we demonstrate the association between up-regulation of v6 and down-regulation of PCBP1 in primary HCC patients, which raises the possibility that v6 overexpression in liver cancer may be partly due to the down-regulation of PCBP1." (PMID 20361869, 2010).
lung adenocarcinoma (4 papers, 2022 to 2024). A carcinoma that arises from the lung and is characterized by the presence of malignant glandular epithelial cells. "This study establishes a critical role for ferroptosis in carbon ion radiation therapy and further demonstrates PCBP1 role in mediating ferroptosis in response to ionizing radiation to inhibit lung adenocarcinoma proliferation." (PMID 39845670, 2024). "Carbon ions promoted an increase in free Fe2+ levels in lung adenocarcinoma cells by down-regulating PCBP1 expression in NSCLC cells." (PMID 39845670, 2024). "To determine the functional role of PCBP1 at promoter regions, we generated PCBP1 CRISPR KO A549 (human lung adenocarcinoma) cells." (PMID 39342995, 2024). "We compared paired normal and tumour tissues of lung adenocarcinoma and found that PCBP1 mRNA levels were low in tumours." (PMID 35907982, 2022). "PCBP1 is responsible for iron transport during various cellular life processes, and its role in regulating lung adenocarcinoma cell death in response to carbon ion radiation is unknown." (PMID 39845670, 2024). "Additionally, carbon ions inhibited the expression of PCBP1, which led to alterations in mitochondrial morphology in lung adenocarcinoma cells." (PMID 39845670, 2024). "Lung adenocarcinoma patients with high PCBP1 expression exhibited longer survival, suggesting that PCBP1 may be a marker of good prognosis." (PMID 38977917, 2024). "PCBP1 acts as a tumor suppressor gene, inhibiting lung adenocarcinoma development." (PMID 38977917, 2024). "We found that PCBP1 inhibits the progression of lung adenocarcinoma." (PMID 35907982, 2022). "Here, we aimed to reveal the biological function of PCBP1 in lung adenocarcinoma (LUAD)." (PMID 35907982, 2022).
ovarian tumor (4 papers, 2014 to 2023). "Here, we firstly describe that downregulation of PCBP1 is significantly associated with clinical ovarian tumor progression." (PMID 32922440, 2020). "Importantly, we further implicated PCBP1 within ovarian tumor biology by the fact that the network built in MetaCore using the 5 overconnected proteins as seed notes and their nearest neighbors, generated a network highly interconnecting all 5 seed nodes." (PMID 25265318, 2014). "Compared to low malignant potential tumors, there was a significant increase in PCBP1 gene expression in malignant ovarian tumors." (PMID 25265318, 2014). "IHC results also showed that PCBP1 expression was positively correlated with p62 expression (R2 = 0.506) and Caspase-8 expression levels (R2 = 0.447) in ovarian tumor samples, respectively." (PMID 32922440, 2020). "We hypothesize that the protein network including PCBP1 contributes to the malignant properties of ovarian tumors, possibly through regulation of the androgen receptor." (PMID 25265318, 2014). "In the library prepared from ovarian tumor tissue, 5 clones with coding sequences were identified using the HMGB1 bait (C1QA, DAG1, RPL29, RSF1, TGM2), and 6 (COMMD1, MIEN1, PCBP1, TBC1D25, ZFR, ZNF428) were identified with the HMGB2 bait." (PMID 32867128, 2020).
acute myeloid leukemia (3 papers, 2012 to 2022). Acute myeloid leukemia (AML) is a group of neoplasms arising from precursor cells committed to the myeloid cell-line differentiation. "In K562, an acute myeloid leukemia cell line, the knockdown of PCBP1 or PCBP2 alone did not affect cell growth." (PMID 36452487, 2022).
colitis (3 papers, 2021 to 2025). Inflammation of the colon. "Poly(rC)-binding protein 1 (PCBP1) deficiency reduces CCL2 and IL-6 production in colitis macrophages." (PMID 39850880, 2024). "The present findings suggest that PCBP1 may be a key downstream target of GFER in colitis." (PMID 41098076, 2025).
thyroid cancer (3 papers, 2018 to 2022). "Supporting this concept, PCBP1 levels are reduced in cultured cells from thyroid cancers compared to cells from normal thyroid tissue." (PMID 35406382, 2022). "From their observations, the authors concluded that UBE4A-regulated ubiquitination and degradation of PCBP1 may be involved in the tumorigenesis of thyroid cancer." (PMID 35406382, 2022). "Additionally, degradation by the 26S proteasome of polyubuiquitinated PCBP1 was observed in thyroid cancer cells." (PMID 35406382, 2022). "Recently, PCBP1 has been shown as a negative regulator of thyroid carcinoma, a negative regulator of EMT related to metastasis in NSCLC, while PCBP1 expression is suppressed in peritoneal gastric cancer metastasis." (PMID 30086790, 2018). "However, in thyroid carcinoma, UBE4A was reported as a ubiquitin ligase that is inversely correlated with PCBP1 protein expression and promotes cancer progression." (PMID 35136024, 2022).
bladder cancer (2 papers, 2024 to 2025). "Research investigating LACTB in bladder cancer revealed that poly(C)-binding protein 1 (PCBP1) suppresses LACTB expression by binding to its mRNA and accelerating its degradation in cancer cells." (PMID 39941048, 2025). "For instance, in bladder cancer, PCBP1 directly promotes LACTB mRNA degradation, thereby regulating its translation and suppressing its tumor-suppressive function." (PMID 39941048, 2025). "PCBP1 protects mitochondrial integrity by destabilizing LACTB mRNA, thereby reducing ferroptosis in bladder cancer cells." (PMID 39941048, 2025). "Similarly, in bladder cancer, LACTB modulates ferroptosis and mitochondrial function by inducing erastin-mediated ferroptosis, which exacerbates mitochondrial dysfunction and ROS production, counteracting the ferroptosis-inhibitory effects of PCBP1." (PMID 39941048, 2025).
esophageal squamous cell carcinoma (2 papers, 2022 to 2023). Esophageal squamous cell carcinoma (ESCC) is a type of esophageal carcinoma (EC) that can affect any part of the esophagus, but is usually located in the upper or middle third. "Here, we found that PCBP1 was highly expressed in esophageal squamous cell carcinoma and PCBP1 knockdown suppressed ESCC cell migration and invasion, suggesting that PCBP1 is an ESCC-associated pro-oncogenic factor." (PMID 35287546, 2022). "PCBP1 is responsible for the significant upregulation of TPM3 in esophageal squamous cell carcinoma." (PMID 37686101, 2023). "In summary, our data suggested that PCBP1 expression levels were significantly increased in esophageal squamous cell carcinoma." (PMID 35287546, 2022). "Taken together, PCBP1 acting as a pro-oncogenic factor enhances TPM3 mRNA stability by directly binding to the 3’UTR of TPM3 mRNA in esophageal squamous cell carcinoma." (PMID 35287546, 2022). "In the current study, we found that PCBP1 was responsible for the significant upregulation of TPM3 in esophageal squamous cell carcinoma." (PMID 35287546, 2022). "Targeting PCBP1 holds great promise for treating esophageal squamous cell carcinoma." (PMID 35287546, 2022). "Therefore, to understand the biological functions of PCBP1 in esophageal squamous cell carcinoma, qPCR, western blotting assays, and cellular functional experiments were performed." (PMID 35287546, 2022). "PCBP1 may be a potential therapeutic target for esophageal squamous cell carcinoma treatment." (PMID 35287546, 2022). "The aim of the current research is to clarify the molecular mechanisms of PCBP1 in upregulating TPM3 expression, providing a potential therapeutic target for the treatment of esophageal squamous cell carcinoma." (PMID 35287546, 2022).
Huntington disease (2 papers, 2022 to 2024). Huntington disease (HD) is a rare neurodegenerative disorder of the central nervous system characterized by unwanted choreatic movements, behavioral and psychiatric disturbances and dementia. "Moreover, abnormal nuclear distribution of PCBP1 has been implicated in the pathogenesis of Huntington's disease (HD), suggesting that RBPs, including PCBP1, may play a role in the pathophysiological processes underlying neurodegenerative conditions." (PMID 38376022, 2024). "Furthermore, abnormal nuclear distribution of PCBP-1 participates in Huntington’s disease (HD) pathogenesis, suggesting that as RBPs, like PCBP-1, may contribute to the pathophysiological processes under neurodegenerative conditions." (PMID 35795237, 2022). "PCBP-1 has important roles in cellular Iron homeostasis, mitochondrial stability, and other cellular activities involved in the pathophysiological process of neurodegenerative diseases, such as amyotrophic lateral sclerosis (ALS) and Huntington’s disease (HD)." (PMID 35795237, 2022).
lymph node metastases (2 papers, 2021 to 2022). "There was a significant association between PCBP1 and tumour invasion, lymph node metastasis and clinical stage." (PMID 35907982, 2022).
pancreatic cancer (2 papers, 2021 to 2024). "Results showed that the percentage of TCGA pancreatic cancer patients harboring PCBP1 mutations was less than 1%." (PMID 39170746, 2024). "Our results provide valuable insights into the development of drugs that target PCBP1, which showed promising synergistic effects with ROS-modulating drugs in pancreatic cancer." (PMID 39170746, 2024). "Discussion: Our results provide valuable insights into the development of drugs that target PCBP1 and identified promising synergistic agents for ROS-modulating drugs in pancreatic cancer." (PMID 39170746, 2024). "Our findings provide a theoretical basis for development and modification of drugs targeting PCBP1, which showed promising synergistic effects with ROS-modulating drugs in pancreatic cancer." (PMID 39170746, 2024). "The expression data from the GSE196009 cohorts further validated the high expression of PCBP1 in pancreatic cancer." (PMID 39170746, 2024). "In this study, we identified PCBP1 as a potential oncogene in pancreatic cancer." (PMID 39170746, 2024). "In conclusion, we identified PCBP1 as a potential oncogene in pancreatic cancer." (PMID 39170746, 2024). "Pan-cancer expression data from The Cancer Genome Atlas Program (TCGA) and GTEx cohorts database showed that the expression of PCBP1 was significantly higher in most types of cancer compared with its expression in normal tissues (23/33), including pancreatic cancer." (PMID 39170746, 2024). "Moreover, PCBP1 affects the alternative splicing of integrin β1, promotes the transformation of integrin β1 subtype A to subtype C in pancreatic cancer cells, and inhibits the metastasis of pancreatic cancer cells in this way13,33." (PMID 34857818, 2021). "Therefore, targeting of PCBP1 by Compound 934 may synergize with ROS-modulating agents to kill pancreatic cancer cells." (PMID 39170746, 2024). "Considering that PCBP1 exhibits highly selective binding to heavily oxidized RNA via o8G residues located nearby on the RNA strand, interfered from the competitive interaction of Compound 934, we propose that Compound 934 may promote ROS agent-induced cell death in pancreatic cancer." (PMID 39170746, 2024). "PCBP2, another member of the hnRNPE family, shares highly homology with PCBP1 in sequence and structure, but it was not correlated with prognosis in pancreatic cancer." (PMID 39170746, 2024). "Although the efficacy of silychristin to suppress pancreatic cancer was low (IC50 = 320 μM), silychristin strongly enhanced ROS agent hydrogen peroxide to induce cell death in pancreatic cancer cells, likely by competitively binding to PCBP1, leading to impaired oxidized RNA elimination." (PMID 39170746, 2024).
steatosis (2 papers, 2023 to 2025). Increased lipid within the cytoplasm of cells. "Mice deficient in liver-specific PCBP1 exhibit oxidative stress, lipid peroxidation, and steatosis, highlighting the role of PCBP1 in mitigating cytoplasmic iron toxicity." (PMID 40358196, 2025). "The hepatic loss of PCBP1 resulted in liver damage with steatosis (elevated liver triglycerides) and dying hepatocytes (elevated plasma alanine transaminase, ALT)." (PMID 36818045, 2023). "Transduction with the variant lacking iron chaperone activity but retaining nucleic acid binding in PCBP1-deleted livers resulted in persistent steatosis and increased triglyceride accumulation." (PMID 36818045, 2023). "The iron-coordinating activity of PCBP1 was essential to prevent steatosis and DNA damage." (PMID 36818045, 2023).
acute kidney injury (1 paper, 2025). Sudden and sustained deterioration of the kidney function characterized by decreased glomerular filtration rate, increased serum creatinine or oliguria. "Although ACE induces ferroptosis in tumor cells by targeting PCBP1/2 and GPX4, previous studies have shown that ferroptosis may cause acute liver injury and acute kidney injury." (PMID 40619432, 2025).
Alcoholism (1 paper, 2018). "Among them, AD-specific module AD_M1 is regulated by SP1, TEAD4, PCBP1 with targets in the pathway of regulation of actin cytoskeleton, cAMP signaling pathway, PI3K-Akt signaling pathway, metabolic pathways, Alcoholism, and PPAR signalling pathway." (PMID 30598117, 2018).
anemia (1 paper, 2023). A reduction in the number of red blood cells, the amount of hemoglobin, and/or the volume of packed red blood cells. "The cytosolic chaperone Poly(rC)-binding protein 1 (PCBP1) delivers iron to ferritin with evidence from Pcbp1 knockout mice, with microcytosis and anemia, that iron delivery to ferritin is required for normal erythropoiesis." (PMID 38153418, 2023).